CD44 (CD44 molecule (IN blood group))
Diseases named in the same sentence as CD44 in open-access papers (continued):
Sharing a sentence is not in itself a finding about the gene and the disease.
cancer (continued). "Moreover, expression of stemness markers such as BMI1 and CD44 was reduced in metformin-treated cells, suggesting that metformin can also target cancer stem cells." (PMID 39796103, 2024). "In addition, CD44+ cancer cells also differentially expressed a stem-cell-related gene implicated in tumorigenesis, polycomb complex protein BMI-1 (BMI1)." (PMID 39335624, 2024). "Due to its pleiotropic action on cancer cells, on the stroma (our own unpublished results) and on signaling from different classes of receptors, CD44 may represent an attractive therapeutic option." (PMID 38761292, 2024). "However, there are relatively few clinical studies about CD44‐targeted therapies in cancer treatment." (PMID 38783892, 2024). "Furthermore, our findings support the established role of CD44 and p27 as valuable biomarkers for cancer diagnosis and prognosis." (PMID 39451527, 2024). "Moreover, the EVs carry surface markers specific to cancer stem cells, namely, CD44, CD133, SSEA4 (stage-specific embryonic antigen-4), and CD326/EpCAM (epithelial cell adhesion molecule) that allows their identification and characterization." (PMID 39473666, 2024). "Increased CD44 levels are correlated with a wide range of cancers." (PMID 39030509, 2024). "Moreover, HA can be integrated into nanomaterials to improve water solubility, biocompatibility, and targetability by specifically binding to CD44-overexpressing cancer cells." (PMID 38799466, 2024). "Furthermore, CD44 has various isoforms, and it would be interesting to investigate the effect of each isoform on chemoresistance and the clinical outcome in various cancers." (PMID 38542115, 2024). "According to the immunohistochemical analysis of the expression level of CD44 in cancer from the HPA database, the study found that CD44 exhibited moderate to strong membranous immunoreactivity, often accompanied with weak cytoplasmic staining, in a few cases of most cancer types." (PMID 38590654, 2024). "The clinicopathological impact of CD44 and its isoforms in promoting tumorigenesis suggests that CD44 could be a molecular target for cancer therapy." (PMID 38672650, 2024). "Recently, growing evidence suggests that CD44 is also relevant in non-cancer diseases." (PMID 38731968, 2024). "CD44 is a cell surface adhesion receptor marker for cancer stemness and metastatic potential." (PMID 38928195, 2024). "Moreover, TTI-101 and SH5-07 target cancer stem cells by downregulating the expression of CD44 and CD133 in 3D models." (PMID 39273033, 2024). "CD44 has been extensively studied in recent years, and clinical and preclinical studies demonstrated its role as a marker of progression and resistance to therapy in several types of cancer." (PMID 38672650, 2024). "CD44 is essential for the rapid growth of various cancer cells." (PMID 38791985, 2024). "However, the function of CD44-positive extracellular vesicles in cancer pathogenesis, especially in pre-metastatic niche formation, remains uncertain." (PMID 39273689, 2024). "And we focus on the biological functions of CD44 in different cancers and cancer‐related signaling pathways regulated by CD44 and provide critical assessment of therapeutic strategies and clinical studies through targeting CD44." (PMID 38783892, 2024). "Cancer stem cells are characterized by the expression of surface stemness markers such as CD44, CD117, and CD133, demonstrating both increased tumorigenicity and reduced platinum sensitivity; these stemness markers are associated with poor overall survival in cancers." (PMID 39684461, 2024). "For instance, direct binding can occur between platelet P-selectin and cancer cell CD44." (PMID 39654896, 2024). "Alone or in cooperation with other signalling pathways, NF-κB promotes the expression of a wide variety of downstream targets, including stem factors (NANOG, SOX2, CD44, and others) and microRNAs, like let-7 and microRNA-21, contributing to self-renewal and expansion features of cancer stem cells." (PMID 38612718, 2024).
cancer (continued). "Furthermore, CD44 serves as a cell surface marker for CSCs and contributes significantly to the maintenance of stemness and regulation of cancer stem cells." (PMID 38191424, 2024). "Disruption of TGF-β signaling downregulated CD44 on ECs, hindering cancer cell adhesion." (PMID 39758992, 2024). "Mechanisms of the anticancer action of tannins include the modulation of signaling pathways in cancer cells, the induction of apoptosis and autophagy, and the reduction of cancer stem cell population by downregulation of the expression of specific biomarkers, such as CD44 and ALDH1." (PMID 38893491, 2024). "Several mAbs against CD44 have been developed as cancer therapeutics." (PMID 38612911, 2024). "Moreover, the regulation of glucose metabolism by CD44 contributes to antioxidant status and drug resistance in cancer cells." (PMID 39408889, 2024). "Although there are few studies on regulating the interaction of CD44 with FN to treat cancer, owing to the key role of FN in cell migration and adhesion, this aspect may be a promising therapeutic strategy in cancer metastasis." (PMID 38783892, 2024). "Furthermore, we extended our investigation to determine the role of CD44 in cancer cell engraftment to vascular ECs in an in vivo mouse model." (PMID 39758992, 2024). "Moreover, in MCF-7 epithelial cells, targeted downregulation of Set7/9 increased the population of cancer stem-like cells (CD44+/CD24−/low) and dedifferentiation of mammospheres, which was associated with a decrease in E-cadherin expression." (PMID 38812048, 2024). "Consequently, as reported for cancer cells, we observed an upregulation of CD44 expression following TGF-β stimulation, while a downregulation of CD44 expression was seen with inhibitor treatment alone or in combination with TGF-β." (PMID 39758992, 2024). "Therefore, accurately detecting and measuring CD44 is of significant importance for clinical diagnosis of cancer." (PMID 38544254, 2024). "Thus, CD44 expressed on cancer cells (including HNSCC) leads to the resistance and survival of these cells." (PMID 39791719, 2024). "CD133 and CD44 are classical cancer stemness markers of ESCC." (PMID 38413558, 2024). "CD44 plays a role in the mechanisms of drug resistance in cancer cells." (PMID 39408826, 2024). "In conclusion, while the majority of the evidence suggests a negative association between CD44 expression and chemotherapy outcomes, the complexity of cancer heterogeneity, treatment variations, and diverse outcome measures warrant cautious interpretation." (PMID 38542115, 2024). "Additionally, the response to stimulus, involving proteins known to be involved in cancer development such as immunoglobulin heavy variable chain, serotransferrin, and CD44 antigen, was the second most enriched process." (PMID 38580967, 2024). "Similarly, sorted CD44+ALDH+ HNSCC cancer cells cultured in ultralow attachment and soft-agar cultures grew as free-floating spheres, which can be propagated with little loss of CSC traits upon several passages." (PMID 39335624, 2024). "It is well known that CD44 is a molecular marker for cancer stem cells (CSCs)." (PMID 38605343, 2024). "Hence, the employment of the CD44 targeting approach in cancer therapy would require meticulous assessment before implementation." (PMID 37953485, 2024). "The binding of CD44 to HA promotes the adherence of cancer cells to the endothelial lining, initiating a series of events that culminate in extravasation—the process through which cancer cells exit the bloodstream and infiltrate surrounding tissues." (PMID 39758992, 2024). "AZD1480 reduced CD44 levels and cancer stem-like cell abundance in most cancer cell lines." (PMID 38553760, 2024). "Importantly, CD44 is commonly accepted as a marker of cancer‐initiating cells (also known as cancer stem cells, CSC) and of EMT." (PMID 37849446, 2024). "For that, reliable and effective CD44 monitoring is a critical focus of cancer research." (PMID 39451710, 2024).
cancer (continued). "In numerous solid tumours, CD44 is an important marker for self-renewing cancer stem cells." (PMID 38221614, 2024). "In addition to cancer-related responses, CD44-ICD is also engaged in neural inflammation in injured nerves and regulates NF-κB expression." (PMID 39201593, 2024). "In addition, they assessed in the spheroid models the populations of cancer stem cells (CSCs), which are crucial for cancer resistance and recurrence, using two different markers: CD44 and CD117." (PMID 39274933, 2024). "The CD44 antibody significantly suppressed the engraftment of cancer cells onto ECs." (PMID 39758992, 2024). "Furthermore, DRS was strongly associated with cancer stem cell markers, including CD19 (R = 0.32; p < 1.9e-13), CD44 (R = 0.21; p = 1.4e-06), and SOX2 (R = 0.29; p = 2.2e-11)." (PMID 38862242, 2024). "However, clinical trials on CD44 in the treatment of cancer are limited, concentrating on targeting CD44v6, an isoform associated with metastasis and invasiveness." (PMID 38783892, 2024). "Clinical studies using CD44‐targeting therapies for cancer treatment." (PMID 38783892, 2024). "Another study indicates that administering a STAT3 inhibitor reduces CD44 expression in biliary tract cancer and may be a promising target for reducing cancer cell stemness in OC." (PMID 39766086, 2024). "CD44 is a membrane glycoprotein with multiple roles in normal development but also cancer." (PMID 38790166, 2024). "Western blot was adopted to assess the expression of cancer stem cell markers CD44, CD24 and ALDH1." (PMID 38526702, 2024). "Obvious colocalization of PEAR1 and CD44 was noted on the cancer cell membrane in the TNBC nest." (PMID 39145451, 2024). "In the mouse model dataset, TPCS cancer cells overexpress the luminal markers Xbp1 and Fgfr3 as well as the basal stem cell markers Itga6 and Cd44, the basal marker Egfr, and the EMT‐related marker Cldn4, suggesting that TPCS are of potential to generate multiple lineages." (PMID 38582099, 2024). "Furthermore, CD44-high cancer stem cells (CSCs) from HNSCC exhibited increased migration, invasiveness, and stemness." (PMID 39273139, 2024). "Furthermore, our insights into CD44-mediated cell-cell adhesion unveil potential therapeutic avenues, warranting further investigation on cancer engraftment." (PMID 39758992, 2024). "CD24 and CD44, like discussed previously, are cell surface markers that are often used to identify cancer stem cells, which have the ability to self-renew and differentiate into various types of cancer cells." (PMID 38523788, 2024). "Upon TEVs docking or uptake by target cells, CD44 could also function as a trigger of signaling pathways impinging on cellular processes related to cancer progression and metastasis, such as proliferation, inhibition of apoptosis, migration or invasion." (PMID 38542421, 2024). "The interaction between MET and CD44 significantly promotes cancer progression and metastasis." (PMID 39769452, 2024). "The protein CD44, which is located on the surface of cells and has the ability to bind to hyaluronic acid (HA), has been found to be expressed at higher levels in multiple types of cancer cells." (PMID 39166136, 2024). "Additionally, MSC-2 shown high expression of cancer-associated fibroblast (CAFs) markers, including FAP, FN1, and CD44." (PMID 38281962, 2024). "Additionally, a positive correlation between CD44 expression and microvessel density has been shown in numerous cancer types." (PMID 38796656, 2024). "CD44 is a transmembrane adhesion molecule involved in multiple physiological responses, including inflammation, leukocyte rolling, and regulating hyaluronan (HA) and cancers." (PMID 39201593, 2024). "CD44 is a CSC marker conserved across cancer types including HNSC." (PMID 38273364, 2024). "CD44-ICD acts as a CD44 signal transductor that regulates the CD44’s cancer-related response." (PMID 39201593, 2024). "Together, CD44 interacts with its ligands plays key roles in cancer progression." (PMID 38783892, 2024).
cancer (continued). "The expression of CD44 elevated in most cancers, predicting unfavorable prognosis." (PMID 38590654, 2024). "Our findings showed that CoQ0 upregulated CD24 expression and downregulated CD44 expression in a concentration-dependent manner, shifting the CD24/CD44 ratio in favor of suppressing the cancer stem-like properties of OECM-1 and SAS cells under normoxia and hypoxia." (PMID 38904007, 2024). "In the context of cancer metastasis observed in TβRIIiΔEC mice, cancer cells may activate the signaling pathway through CD44, a well-known cancer stem marker, whose expression is increased by TGF-β signaling." (PMID 39758992, 2024). "CD44 regulates cancer stemness, including self-renewal and metastasis." (PMID 38881904, 2024). "Altogether, CD44 is considered a factor in drug resistance and invasion in cancers." (PMID 39091989, 2024). "Several other studies have indicated that CD44 may serve as a promising marker for the progression of cancer." (PMID 38544254, 2024). "The conclusion of the bioprinted model of breast cancer–vessel–bone architecture represents a significant advancement in tissue engineering, with functional blood vessels expressing crucial markers like endothelial vascular CD31, cancer stem cell CD44, and osteogenic OCN." (PMID 38786516, 2024). "Furthermore, EIF4G2 KD resulted in enrichment in cells expressing higher levels of markers such as CD133, CD44 and ALDH1A1 associated with aggressiveness, often referred to as cancer stem cells (CSC)." (PMID 38388710, 2024). "This is partially similar to TPCS in human cancer which overexpressed CD44 and TM4SF1." (PMID 38582099, 2024). "Overall, the multifaceted roles of CD44 in cancer progression and an important regulator of stemness provide a compelling rationale for the continued research and translating these insights into effective therapeutic strategies for cancer management." (PMID 38612911, 2024). "CD44-positive CAFs sustain the stemness and drug resistance of cancer cells." (PMID 38796656, 2024). "Cancer stem cells such as CD44 and CD133 have also been identified in tissues from colorectal cancer liver metastases, and an increase in CD44v9 expression in liver metastasis cases in this study is presumed to result from shedding from the primary and metastatic sites." (PMID 38672639, 2024). "EGFR and MAPK signaling pathway components as well as the EMT transcription factor SLUG (SNAI2;) or the putative cancer stem cell marker CD44 may be considered, at least partially, as effective cancer targets or surrogate biomarkers." (PMID 38378518, 2024). "Simultaneously, the elevated engagement of CD44 points to a potential mechanism by which cancer cells may enhance their adhesive properties, favouring dissemination." (PMID 38597415, 2024). "Cancer cells with CD44 overexpression present enhanced invasiveness and chemoresistance." (PMID 38791985, 2024). "Hence, this scoping review aims to systematically review the current clinical literature to elucidate the impact of CD44 on chemotherapy treatment outcomes in cancer patients, addressing the existing uncertainties in this vital area of cancer research." (PMID 38542115, 2024). "Whether or not ALDH plays an essential role in conferring CSC traits to cancer cells like CD44 is currently unreported, but ALDH as a therapeutic target in several cancers has entered different phases of clinical trials." (PMID 39335624, 2024). "The CD44/STAT3 axis is involved in cancer progression and therapy resistance." (PMID 39766086, 2024). "Several pharmacological inhibitors for CD44 have been developed as anti-cancer agents." (PMID 38612911, 2024). "Hyaluronic acid is a ligand of CD44, a receptor which plays various roles in cancer cell survival." (PMID 39791719, 2024).
cancer (continued). "Shared interacting protein CD44 is a cancer stem cell marker for CRC16." (PMID 39715885, 2024). "We suspect that DOT1L may affect WNT signaling by influencing expression of CTNNB1 and promote the formation of cancer stem cells by promoting CD44 expression." (PMID 38495505, 2024). "CD44 has been extensively identified as a cancer stem cell marker in multiple cancer types." (PMID 38985127, 2024). "With all these data taken together, CD44 could represent a potential therapeutic target for treating KRAS-dependent carcinomas." (PMID 38672650, 2024). "In short, these outcomes strongly indicate that CD44 might be a useful biomarker for most cancer types." (PMID 37117249, 2023). "Furthermore, our IHC data also revealed an increased expression of cancer stemness markers CD44, CD133, and c-kit within the corpus gland of the H+/K+ ATPase-Cre; LKB1L/L; PTENL/L mice." (PMID 38136437, 2023). "Expression of this CD44 variant maintains the epithelial phenotype, indicating a direct connection between G4-mediated alternative splicing regulatory mechanism and phenotypic plasticity during EMT in cancer." (PMID 36909167, 2023). "In contrast, primary tissue-derived human CD44+ EpCAM+ ALDH1high ERα− cancer stem cells showed an abrogation by mTOR inhibitors during combination treatment with tamoxifen, which failed to prevent sphere formation alone until an mTOR inhibitor was introduced alongside it." (PMID 37904250, 2023). "CD44, as a marker of cancer stem cells (CSCs), was negatively associated with both DFS (p = 0.039) and OS (p = 0.012) in the present study." (PMID 37173968, 2023). "Taken together, above results elucidated that CD44 could act as a therapeutic response biomarker in various cancer." (PMID 37117249, 2023). "Functionally, CBX2, which was highly correlated with CD44, shaped a cancer stem cell-like phenotype by positively regulating cell-cycle progression, proliferation, invasion, metastasis, wound healing, and radiation resistance, revealed by combining bulk RNA-seq and scRNA-seq datasets." (PMID 37980163, 2023). "The spheroids were composed of CD44‐stained CSCs and differentiated cancer cells at a 1:1 ratio and embedded in Matrigel mixed with or without electrostatically charged polymers to simulate the lower, higher, and neutral electrostatic potentials in the peripheral environment." (PMID 36925705, 2023). "Cancer stem cells are identified and can be isolated based on the expression of specific cell-surface proteins that act as molecular biomarkers, among which the most frequent markers are CD44, CD133, CD24, EpCAM, and LGR5." (PMID 37367867, 2023). "Many studies reported that high expression of CD44 predicts poor prognosis in various cancers." (PMID 37835592, 2023). "The Pd-Pt-GOx/HA system specifically targets CD44-overexpressed cancer cells and possesses intracellular Hyase-responsive GO, catalase (CAT), and peroxidase (POD)-like activities as well as glutathione (GSH) oxidation capacity, significantly enhancing therapeutic efficacy and biosafety." (PMID 37376161, 2023). "Taken together, it is reasonable to speculate that CD44 may play an essential role in cancer immunity and ultimately influence prognosis." (PMID 37117249, 2023). "Furthermore, CD44, a surface adhesion molecule and marker of cancer stem cells, has also been found to mediate tumor cell aggregation in a patient-derived breast cancer model through homophilic interaction and downstream activation of FAK signaling." (PMID 37442876, 2023). "AUC analysis was employed for identification of the most cancer-specific CD44+ subtype." (PMID 36100762, 2023). "Accordingly, a relative increase of certain markers can be detected in the profile of cancer cell-derived EVs compared with normal primary astrocyte-EVs: CD44 and CD90 were elevated in LN18-EVs; CD36, CD54, CSPG4, and GD2 in LN229-EVs; CD13, CD49e, CD49f, and CD90 in NCH82-EVs." (PMID 37803478, 2023).